IL2 (interleukin 2)
Diseases named in the same sentence as IL2 in open-access papers (continued):
Sharing a sentence is not in itself a finding about the gene and the disease.
melanoma (continued). "In those studies, IL12/15/18-activated NK cells exhibited a stable and persistent enhanced ability to control B16 melanoma cells in vivo, in a mechanism dependent on IL2 produced by CD4+ T cells." (PMID 34187852, 2021). "For example, Zingg at al. observed that anti-CTLA-4 or IL-2 immunotherapy leads to TNFα amplification and T cell infiltration, resulting in EZH2 overexpression and loss of tumor control in melanoma mouse models." (PMID 34575678, 2021). "There are several examples of chemical modifications of IL-2 or construction of innovative materials for its delivery in the therapy of advanced melanoma." (PMID 33546290, 2021). "Early preclinical studies demonstrated superior efficacy of BEMPEG monotherapy to native IL‐2 in an aggressive murine melanoma mouse model." (PMID 33152115, 2021). "Cytokine therapy has FDA approved indications with IL-2 for renal cell carcinoma and melanoma, and type I interferon for adjuvant therapy of melanoma, and in CML and MPNs." (PMID 33732652, 2021). "For example, treatment with interleukin-2 (IL-2) is a long-existing immunotherapeutic approach to melanoma and metastatic renal cell carcinoma." (PMID 33809187, 2021). "The authors reported 99mTc-IL2 uptake in 15 out of 21 (71%) melanomas lesions and 2 out of 9 (22%) benign cutaneous lesions." (PMID 34445532, 2021). "Early studies characterized the efficacy of IL-2 fused with an antibody specific for GD2 in models for melanoma and neuroblastoma." (PMID 33803078, 2021). "Further, ABCB5+ melanoma CSCs preferentially inhibited IL-2–dependent T-cell activation in a CD86-dependent manner and induced CD4+CD25+FoxP3+ regulatory T cells (T-regs)." (PMID 33806296, 2021). "Adoptive cell therapy with a nonmyeloablative preparative regimen using either tumor-infiltrating lymphocytes or T-cell receptor-transduced cells, combined with IL-2, can mediate a complete and durable regression of melanoma brain metastases in patients." (PMID 33466236, 2021). "A study utilizing the B16-OVA mouse melanoma model demonstrated that the anti-tumor effect of an IL-2/anti-IL-2 complex combined with anti-CTLA-4 mAbs was dependent on both NK cells and CD8+ T cells." (PMID 34503073, 2021). "For example, the IL-2 cytokine aldesleukin (Proleukin®) targeting the IL-2/IL-2R pathway was approved for subsets of patients with kidney cancer and melanoma." (PMID 33918635, 2021). "With FDA approval, anti-PD-1 antibodies became the first-line treatment for advanced melanoma over ipilimumab, dacarbazine, and high-dose IL-2 due to their superior response rates, durability, and lower rates of systemic toxicity." (PMID 34885172, 2021). "Melanoma has “traditionally” been the tumor that is most vulnerable to immunotherapeutic strategies, since the employment of high-dose recombinant interleukin 2 (IL-2) in the 1980s, and it is also quite sensitive to ICIs." (PMID 34959474, 2021). "For example, transforming growth factor-β (TGF-β) and interleukin-2 (IL-2), which, respectively, suppress local tumor immune responses and amplify the activation of melanoma-specific T-cell responses, can be combined to treat metastatic melanoma." (PMID 33628850, 2021). "For example, Aldesleukin (Proleukin®) is a synthetic form of IL-2 produced by recombinant DNA technology and is approved for the treatment of kidney cancer and melanoma." (PMID 34205019, 2021). "Human TILs grown from resected melanomas in the presence of recombinant IL-2 showed high potency against autologous melanomas." (PMID 34140957, 2021). "In support of this, proliferating ICOS + Tregs in melanoma patients treated with high-dose IL-2 have been reported to co-express high levels of CD73 and CD3940." (PMID 34650224, 2021). "From 1987 to 1992, they analyzed 86 melanoma patients who were treated with TILs followed by high-dose IL-2 and showed a 34% overall responsive rate (ORR), with and without prior IL-2 exposure." (PMID 34553029, 2021).
melanoma (continued). "Current immunotherapies for advanced melanoma are designed to actively stimulate the patients’ own immune system by boosting T-cell activation (IL-2) or by blocking immune checkpoints." (PMID 34572949, 2021). "The immunocytokine (IC) fusion protein, hu14.18-IL2 that consists of human recombinant IL2 (hrIL2) fused to humanized anti-disialoganglioside (GD2) monoclonal antibody (mAb) has been evaluated in humans for the treatment of melanoma and neuroblastoma." (PMID 34383787, 2021). "A combination of DOX/IL-2/IFN-g included in a temperature-sensitive polypeptide hydrogel has been developed for the effective treatment of melanoma." (PMID 33800402, 2021). "In another study, the sequential combination of fotemustine, cisplatin, IFN-α, and IL-2 showed acceptable clinical activity, especially in melanoma brain metastatic patients." (PMID 33466236, 2021). "Briefly, the technique of site-specific delivery of DOX/IL-2/IFN-g utilizing the polypeptide hydrogel presented a viable technique for effective melanoma treatment." (PMID 33800402, 2021). "A number of approaches are being pursued to therapeutically exploit immunostimulatoroy cytokines in melanoma, particularly involving IL-2 and IL-15." (PMID 36284898, 2021). "The upregulation of IL-1β, IL-2, IL-6, and IL-12 mRNA expression was significant in PBMCs co-cultured with melanoma cells depigmented by both tyrosinase inhibitors, compared to pigmented cells." (PMID 34072104, 2021). "A study of high-dose IL-2 therapy on melanoma patients showed Treg is the most proliferative cell type after IL-2 administration, and the accumulation of Treg is correlated with poor prognosis." (PMID 35008589, 2021). "A similar IL-2 mutant immunocytokine targeting EGFR had a synergistic effect with anti-PD-L1 in melanoma models." (PMID 33803078, 2021). "A more localized approach evaluated the intratumoral administration of the IL-2 EDB-targeting immunocytokine in 24 stage III melanoma patients and was well-tolerated, with complete responses seen in 44% of treated lesions and 45% of non-treated lesions." (PMID 33803078, 2021). "TILs were expanded by in vitro culture in the presence of recombinant interleukin 2 (IL-2) and transfused into the patients to treat melanoma." (PMID 34650571, 2021). "As a second model, interleukin-2 (IL-2)-activated human SMCY.A2 CTL27, which recognize an HLA-A2-restricted antigen encoded on the y chromosome, were confronted with male human melanoma cell lines BLM or MV3." (PMID 34471116, 2021). "Further, TA99 in combination with IL-2 and T cell vaccines is effective for the elimination of established tumors in the B16 model of melanoma." (PMID 33520112, 2021). "Nevertheless, IFN-α and IL-2 were clinically approved for the treatment of different malignancies such as hairy cell leukemia, follicular non-Hodgkin lymphoma, melanoma, and Kaposi's sarcoma (IFN-α) or renal cell carcinoma and melanoma (IL-2)." (PMID 35097027, 2021). "Overall, however, further mechanistic insight into the role of intralesional IL2 in the tumor microenvironment of melanoma is required." (PMID 32455916, 2020). "Our findings are in conceptual agreement with a recent report demonstrating that T cells with silenced PPP2R2D produced more IL-2 and other cytokines when transferred into mice along with melanoma cells." (PMID 32897879, 2020). "Interleukin-2 is thought to mediate antitumor cellular immune responses through lymphocyte activation, and is currently approved for the IV treatment of melanoma and renal cell carcinoma." (PMID 31858848, 2020). "IL-2 was the first immunotherapy to influence the outcome of advanced melanoma patients, but its harsh toxicity with cardiovascular, respiratory, and infectious complications restrained its use." (PMID 31979325, 2020). "IL-2-based compounds in combination with CTLA-4 blockade should be studied in advanced melanoma patients who fail to benefit from first-line PD-1 blockade." (PMID 31998643, 2020).
melanoma (continued). "By using these complexes, a thousand times less IL-2 was required for T-cell activation and expansion compared to soluble IL-2, and a delay in tumor growth was achieved in a melanoma model." (PMID 32917054, 2020). "We performed a prospective randomized study to determine if the ORR of SBRT + IL-2 was greater than IL-2 monotherapy in patients with advanced melanoma." (PMID 32467299, 2020). "IL2 is also used as an adjuvant in the treatment of patients with melanoma, advanced colorectal cancer or ovarian cancer with autologous dendritic cells stimulated by autologous tumor lysate, as well as in the treatment with viral vaccines." (PMID 32582698, 2020). "Ipilimumab was also able to trigger ADCC via the engagement of FcyRIIIA receptors present on primary NK cells as well as NK cells and γδT cells activated by IL-2 by reacting with CTLA-4 present on melanoma cell lines and tissues." (PMID 32117298, 2020). "The utility of IL-2 as an antitumor agent was approved by the FDA in patients with advanced melanoma and renal cell carcinoma (RCC) decades ago." (PMID 33266177, 2020). "Interleukin (IL)-2 treatment was the first approved immunotherapy for use in melanoma, prescribed alone, or combined with other drugs." (PMID 32580338, 2020). "Although high doses of IL-2 showed promising results in metastatic renal cell carcinoma and melanoma, the toxicity and cost limited its application in a large population." (PMID 32423420, 2020). ",22, 23, 24 Cancer vaccines targeting gp100 particularly in combination with recombinant interleukin-2 (IL-2) resulted in some benefit for melanoma patients." (PMID 33209978, 2020). "To test if the inhibitor is compatible with immunotherapy, we used a recently developed model, the PDXv2 model, where human melanoma is grown in an immunocompromised mouse transgenic for human IL-2 (hIL2-NOG mice)." (PMID 32571801, 2020). "Only two cytokines interferon-alpha and IL2 have been approved by the FDA for treatment of refractory melanoma and renal cell cancer, and are rarely used as monotherapy." (PMID 33381115, 2020). "For example, both interferon-α (IFN-α) and interleukin-2 (IL-2) are administered to melanoma patients." (PMID 32714859, 2020). "Recombinant interleukin-2 (rIL-2) is thought to mediate anti-tumor cellular immune responses through lymphocyte activation and is currently a therapy for melanoma and renal cell carcinoma." (PMID 31858848, 2020). "Progress in immunotherapy and the development of T cell ICIs such as CTLA-4 and PD-1 inhibitors have further limited the use of IL-2 as a treatment for melanoma patients in high doses." (PMID 32580338, 2020). "The DETC cell line AU16, derived from C3H mice, is an IL-2-dependent cell line and cytotoxic to melanoma cell lines and chemo-induced fibrosarcoma in vitro." (PMID 32765487, 2020). "High-dose interleukin-2 (HD IL-2) therapy has for decades served as one of the immunotherapies for advanced melanoma treatment." (PMID 32948031, 2020). "High-dose IL2 is considered the first effective cancer immunotherapy, since the treatment can lead to complete responses for melanoma or renal cell carcinoma patients with only a few patients experiencing recurrence." (PMID 33216834, 2020). "IL-2 based therapies have been accepted for the treatment of malignant melanoma and renal cell carcinoma." (PMID 32570871, 2020). "For example, high numbers of neutrophils and monocytes in peripheral blood are associated with poor survival in metastatic melanoma and serve as prognostic factors for overall survival in IL-2 treated melanoma patients." (PMID 32610601, 2020). "We observed that patients with melanoma or renal cell carcinoma (RCC) who had radiation for urgent palliation in the week before IL-2 had a surprisingly high objective response in lesions that were not radiated following high-dose IL-2." (PMID 32467299, 2020).
melanoma (continued). "At present, the use of intralesional IL-2 for metastatic and in-transit melanoma is well supported; however its use in other malignancies is not well described." (PMID 33704189, 2020). "Serum VEGF levels have also been previously evaluated as a predictive biomarker of response to identify patients more suitable for treatment with interleukin 2 (IL-2) in advanced melanoma." (PMID 32695680, 2020). "IL-2-induced NK cell infiltration into lung, liver and subcutaneous B16 melanoma was mediated by endothelial VCAM-1 interacting with VLA-4 on NK cells." (PMID 33262763, 2020). "A more promising procedure has been proposed in melanoma where tumor-infiltrating T lymphocytes (TILs) isolated from the tumor tissue used for PDX generation were expanded in vitro by human interleukin 2 (IL2) before injection in tumor-bearing PDX mice." (PMID 32714605, 2020). "In following studies, the Rosenberg group demonstrated the retroviral transduction of anti-melanoma TIL with the IL-2 gene or with an inducible IL-12 gene placed under the control of a nuclear factor of activated T cells- (NFAT)-responsive promoter." (PMID 33488585, 2020). "A very interesting ongoing phase 1/2 clinical trial is investigating the efficiency of an IL-2 pegylated molecule (Bempegaldesleukin) in combination with nivolumab for the treatment of melanoma, with promising primary results." (PMID 31979325, 2020). "Of the eight patients randomized to IL-2 whose melanoma progressed after the first imaging, seven agreed to participate in the crossover portion of the study." (PMID 32467299, 2020). "The inhibition of DETCs on melanoma is IL-2 dependent and needs a close contact between DETCs and melanoma." (PMID 32765487, 2020). "Strikingly, further supplementation of intralesional IL2 + imiquimod with retinoid creams achieved a 100% CR in treatment of melanoma metastases." (PMID 32455916, 2020). "One of the newest approaches to cancer immunotherapy is the combination of immune checkpoint inhibitors and recombinant IL2 for the treatment of melanoma and renal cell carcinoma." (PMID 32582698, 2020). "Metastatic melanoma trials showed that IL-2 treatment shrinks advanced melanomas with an objective response rate of 16%, with a median duration of response of 8.9 months." (PMID 32714859, 2020). "Recombinant IL-2 is approved as a therapy for melanoma but is limited by severe systemic toxicity and the preferential induction of proliferation of Foxp3+ regulatory T cells (Tregs) that express the high-affinity IL2Rα chain CD25." (PMID 32019478, 2020). "Unexpectedly, we also observed that although not affected by PD-1/PD-L1 signaling, the KO6 T cell clone globally produced lower levels of IFN-γ and IL-2 than the WT4 T cell clone especially in response to melanoma cell lines." (PMID 32001504, 2020). "We report that ACT supported by NKTR-214 increases the proliferation, homing and persistence of anti-tumor T cells compared to ACT with IL-2, resulting in superior antitumor activity in a B16-F10 murine melanoma model." (PMID 32005809, 2020). "Autologous TILs were transferred in conjunction with IL2 after ex vivo expansion with IL2, which mediated a durable and completed tumor regression in 22% of the heavily pretreated melanoma patients." (PMID 33381115, 2020). "HD IL2 increased overall survival (OS) in patients with renal cell carcinoma and progressive melanoma who was previously treated with a PD-1 or PD-L1 inhibitor compared to patients without pretreatment with anti-PD-1/PD-L1." (PMID 32582698, 2020). "As administration of IL-2 at high dose in patients with metastatic RCC or advanced melanoma achieved significant clinical responses, the treatment was subsequently approved by the FDA." (PMID 33266177, 2020). "Although high‐dose IL‐2 remains a good treatment option for a subgroup of metastatic renal cancer and melanoma patients, its more widespread use has been limited by its toxicity, relatively short half‐life, and variability in patient responses." (PMID 32480431, 2020).
melanoma (continued). "Here, the authors show that a modified IL-2 cytokine (NKTR-214) can outperform IL-2 in a melanoma mouse model." (PMID 32005809, 2020). "This allowed a more in-depth study of this lymphocyte growth factor, thus giving it the name IL-2, which was approved for the treatment of metastatic renal cell cancer in 1992 and advanced melanoma in 1998." (PMID 32610601, 2020). "Ferrari de Andrade and colleagues used a human A2058 melanoma cell line in an intravenous model in NSG mice reconstituted with human NK cells whose survival was supported by continuous injections of IL-2." (PMID 32570871, 2020). "Systemic IL-2 in combination with gp100 peptide-vaccine in patients with melanoma has delivered significant efficacy in terms of objective response and progression-free survival compared to IL-2 monotherapy." (PMID 33679703, 2020). "Proleukin®/IL-2 is a form of recombinant IL-2 used for the treatment of cancers such as, malignant melanoma and metastatic renal cell carcinoma." (PMID 33193321, 2020). "Despite the adverse effects, high doses of IL2 have been used to treat melanoma and renal cell carcinoma with positive results." (PMID 31614774, 2019). "The CSPG4-specific CAR-T cells recognized the CSPG4-positive melanoma cell line A375M and responded with the production of IL-2, TNF, and IFNγ, while the CSPG4-negative target cell line 293T was not recognized." (PMID 31426437, 2019). "Although responses to IL-2 have been reported in clinical trials in patients with various malignancies, only clinical trials for renal cell carcinoma and melanoma observed efficacy of IL-2." (PMID 30693030, 2019). "IL-2 is a T-cell growth factor that has documented efficacy against human melanoma and melanoma in murine models, and has been studied in naturally occurring CMM, combined with tumor surgery and radiotherapy." (PMID 30759787, 2019). "As far as the imaging of T lymphocytes in the tumour environment is concerned, both iodinated and techenetiated IL2 have been used for imaging of squamous cell carcinoma of the head and neck, renal cell carcinoma and in melanoma." (PMID 31091813, 2019). "Melanoma patients with CNS involvement require higher doses of IL-2, which is challenging due to adverse events such as neurotoxicities and the need for hydration." (PMID 32309611, 2019). "Noteworthy, elevated serum levels of VEGF-A were previously shown to be associated with poor clinical response and decreased overall survival in melanoma patients treated with high-dose interleukin-2 or with ipilimumab." (PMID 31227006, 2019). "Low-dose total body irradiation exhibited a synergistic immune-mediated anti-tumor effect when used in combination with IL-2 in a murine metastatic malignant melanoma model." (PMID 31179236, 2019). "Surprisingly, a recent meta-analysis showed that rates of complete response were similar with high and intermediate dose of IL-2 for the treatment of melanoma." (PMID 31134073, 2019). "Transducing melanoma TIL to continually secrete IL-2 bypassed the need for exogenous administration of IL-2 to the patient." (PMID 30842774, 2019). "In the early 1980s, Rosenberg and collaborators explored the therapeutic potential of autologous lymphokine activated killer (LAK) cells in combination with high-dose IL-2 in patients with advanced metastatic renal cancer and melanoma." (PMID 31340613, 2019). "IL-2 exhibits antitumor effects in a small subpopulation of patients with antigenic tumor types such as malignant melanoma or renal cell cancer." (PMID 30808414, 2019). "TNF, IFN and IL-2 have been used to treat a variety of a human solid tumours, including melanoma, renal cell carcinoma, multiple myeloma and ovarian cancer." (PMID 30987001, 2019). "Collected data from several clinical trials evaluating the efficacy of recombinant IL-2 therapy in the 1980s showed that a small fraction of melanoma patients experienced durable complete responses." (PMID 31028434, 2019).